HDAC4 (histone deacetylase 4)
Diseases named in the same sentence as HDAC4 in open-access papers (continued):
Sharing a sentence is not in itself a finding about the gene and the disease.
Atrophy (6 papers, 2018 to 2025). Any weakening or degeneration, especially through lack of use. "Nuclear HDAC4 has been reported to induce muscle atrophy in various models of neural injury and disuse, including denervation, spinal muscular atrophy (SMA), and immobilization through shared and unique mechanisms." (PMID 40998017, 2025). "Accordingly, in other models of muscle atrophy, an increase of HDAC4 and myogenin has been reported." (PMID 35408999, 2022). "Histone deacetylase 4 (HDAC4) has recently been found to be closely related to muscle atrophy, but the underlying mechanism of HDAC4 in denervation-induced muscle atrophy have not been described clearly yet." (PMID 34276308, 2021). "Moreover, recent work has demonstrated that HDAC4 is an important regulator of Gadd45α in denervation-induced muscle atrophy, and the knockout of HDAC4 can attenuate denervation-induced muscle atrophy." (PMID 33246401, 2020). "HDAC4 also regulates cell division, cell cycle, apoptotic process, and cell differentiation via CDKN1A and SIK1, involving in denervation-induced muscle atrophy." (PMID 34276308, 2021). "Because HDAC4 is a key player in the regulation of MuRF1 and Atrogin-1 during neurogenic muscle atrophy, the effect of PHA-665752 on the denervation-mediated increase of HDAC4 expression was studied by qRT-PCR and western blot." (PMID 30195792, 2018).
breast tumors (6 papers, 2006 to 2023). "Thus, miR-125a-5p is inversely correlated with HDAC4 in human breast tumors." (PMID 25504437, 2015). "Explicitly, genomic profiling of these epigenetic enzymes displayed increases in HDAC1, 2, 8, 10, 11, and Sirtuins (SIRTs) 6 and 7, and decreases in HDAC4-7, -9, and SIRT1-4 levels, respectively, in TCGA breast tumors." (PMID 38003678, 2023).
developmental delay (6 papers, 2014 to 2025). "Although deletions reported in most patients affect many genes, it seems that the loss of the Histone Deacetylase 4 (HDAC4) gene leads to haploinsufficiency and drives the phenotype typically seen in these patients (brachydactyly type E, developmental delays, and Behavioral Problems)." (PMID 36192675, 2022).
diabetic cardiomyopathy (6 papers, 2021 to 2025). Diabetic cardiomyopathy is a disorder of the heart muscle in people with diabetes. "However, depleting HDAC4 has been implicated to mechanistically repress the apoptosis of cardiomyocyte in diabetic cardiomyopathy." (PMID 35091534, 2022). "Previous studies have found that catalpol inhibits cardiomyocyte cell death via the Neat1/miR-140e5p/HDAC4 axis in diabetic cardiomyopathy." (PMID 36353492, 2022). "Overexpressing HDAC4's N‐terminal fragments prevents HDAC4‐dependent diabetic cardiomyopathy." (PMID 38116061, 2023). "Similarly, HDAC4 inhibition proved to be beneficial against the development of diabetic cardiomyopathy." (PMID 36568083, 2022). "In addition, both miR-140-5p overexpression and HDAC4 silencing have been revealed to reduce the apoptosis of cardiomyocytes, thus exerting cardioprotective effects against diabetic cardiomyopathy." (PMID 34526481, 2021).
diffuse large B-cell lymphoma (6 papers, 2015 to 2023). "In fact, ectopic expression of HDAC4 in B cell-type diffuse large B cell lymphoma cells results in reduced miR-155-induced proliferation and induction of cell death." (PMID 36762207, 2023). "HDAC4 was inhibited by miR-155 in human diffuse large B cell lymphoma (DLBCL) cells, resulting in up-regulation of downstream genes and induction of uncontrolled cell proliferation." (PMID 34880761, 2021). "Indeed, ectopic expression of HDAC4 in diffuse large B cell lymphoma cells of the B cell type leads to reduced miR-155-induced proliferation and induction of cell death." (PMID 36762207, 2023). "Importantly, meta-analysis of microarray data from diffuse large B-cell lymphoma patients found that miR-155 expression correlated negatively with Bcl6 and Hdac4 expression, strongly supporting the role of the miR-155/Bcl6/Hdac4 pathway in the pathogenesis of human leukemias." (PMID 29354135, 2017).
eating disorder (6 papers, 2015 to 2023). A broad group of psychological disorders with abnormal eating behaviors leading to physiological effects from overeating or insufficient food intake. "In humans, mutations in HDAC4 have been linked with eating disorders." (PMID 36994871, 2023). "Finally, mutations in the HDAC4/Hdac4 genes have been associated with eating disorders in both humans and mice." (PMID 36189793, 2022). "Thus, mutations altering the functional relationship between the transcription factor ESRR α and the transcriptional repressor histone deacetylase 4 (HDAC4) could be linked to the development of eating disorders." (PMID 37299557, 2023). "Although histone modifications have not been comprehensively studied in AN, histone deacetylase 4 (HDAC4) – an enzyme that facilitates the removal of acetyl groups from histones, is differentially methylated in AN and other eating disorders." (PMID 32772766, 2020). "Further, recent research has identified mutations on two specific genes that have been associated with increased risk of developing eating disorders in families: estrogen-related receptor α (ESRRA) and histone deacetylase 4 (HDAC4)." (PMID 26380085, 2015).
epilepsy (6 papers, 2009 to 2025). A brain disorder characterized by episodes of abnormally increased neuronal discharge resulting in transient episodes of sensory or motor neurological dysfunction, or psychic dysfunction. "It indicates that activation of HDAC4 promotes neuronal excitotoxicity, a hallmark of epilepsy." (PMID 39563472, 2024). "Silencing of the HDAC4 gene reduces seizure activity and improves cognition in rat epilepsy models, accompanied by increased expression of the α1 and α4 subunits, both of which are commonly associated with extrasynaptic locations." (PMID 41170380, 2025). "As outlined in Section 6.3, genetic and epigenetic interventions—including HDAC4 silencing and microRNA-155 inhibition—modulate extrasynaptic receptor function, highlighting their therapeutic relevance in epilepsy, stroke, and neurodevelopmental disorders." (PMID 41170380, 2025). "Treatment of latently infected cells with sodium valproate, an inhibitor of histone deacetylase 4 (HDAC4) and routinely used to treat epilepsy and bipolar disorder, causes changes in chromatin structure around the viral major IE promoter." (PMID 31580403, 2019). "Further study is required to reveal the interplay between HDAC4 and epilepsy." (PMID 19672313, 2009). "Among these, the numbers of variants annotated to curated epilepsy, seizure-associated, and morbid OMIM genes were 6, 22, and 45, respectively, and HDAC4 c.2851A>T (p.Arg951*) in IS01 is the only non-silent variant in curated epilepsy or seizure-associated genes." (PMID 35937050, 2022). "Glial-specific inhibition of HDAC4, a central repressor of SIK3 signaling, results in a constitutively active glial buffering program that dramatically suppresses seizure and extends life span in a classic epilepsy model." (PMID 33646119, 2021).
Hypertension (6 papers, 2019 to 2024). The presence of chronic increased pressure in the systemic arterial system. "This link is likely due to HDAC4's ability to promote reactive oxygen species- (ROS-) dependent vascular inflammation and the development of hypertension in spontaneously hypertensive rats." (PMID 35814270, 2022). "Recently, it was reported that HDAC3 and HDAC4 mediate hypertension such as in deoxycorticosterone acetate (DOCA)-salt-induced hypertensive rat and SHR, respectively." (PMID 30830950, 2019). "Histone deacetylase 4, HDAC4, has been identified as a crucial regulator of cardiac function, mediating vascular inflammation involved in the pathophysiology of hypertension, and has been recognized to play a pivotal role in myocardial ischemia–reperfusion injury." (PMID 38326862, 2024). "However, dysfunction of HDAC4, which often occurs during aging, may precipitate conditions like hypertension, cardiovascular diseases (CVDs), and neurodegeneration." (PMID 35814270, 2022).
neuroblastoma (6 papers, 2015 to 2024). Neuroblastoma (NB) is the most common solid, extracranial childhood tumor. "Experiments in human-derived SH-SY5Y neuroblastoma cells and rat cortical neurons detected increased histone deacetylase 4 (HDAC4) protein resultant to MeHg exposure." (PMID 31717489, 2019). "SH-SY5Y neuroblastoma cells treated with MeHg 1 μM for 12 and 24 h showed a significant increase of HDAC4 protein and gene expression, whereas the HDACs isoforms 1–3, 5, and 6 were unmodified." (PMID 28154524, 2017). "A recent study revealed an increased expression of histone deacetylase 4 (HDAC4), transcription factors specificity protein 1 (SP1) and 4 (SP4) in neuroblastoma (SH-SY5Y) Hg-treated cells." (PMID 35454102, 2022). "To confirm the involvement of HSV-1 in HDAC4 nuclear accumulation we used the SH-SY5Y neuroblastoma cells transfected to express HDAC4 and infected or not with HSV-1." (PMID 37261502, 2023).
non-small cell lung carcinoma (6 papers, 2016 to 2024). A group of at least three distinct histological types of lung cancer, including non-small cell squamous cell carcinoma, adenocarcinoma, and large cell carcinoma. "For example, inhibition of HDAC4 reduces viability of non-small cell lung cancer." (PMID 27295551, 2016). "We showed that HDAC4 directly interacted with GAC and deacetylated GAC at Lys311 in non-small cell lung cancer cells, which reduced GAC ubiquitination and increased GAC activity." (PMID 35864951, 2022). "As for non-small cell lung cancer, acriflavine, which inhibits the development of HIF-1α/β dimers, panobinostat, which degrades HIF-1α and histone deacetylase 4 (HDAC4), and oroxylin A, which binds directly to the HIF-1α bHLH-PAS domain, can reduce hypoxia-induced cisplatin resistance." (PMID 37460927, 2023).
pulmonary fibrosis (6 papers, 2017 to 2024). Chronic progressive interstitial lung disorder characterized by the replacement of the lung tissue by connective tissue, leading to progressive dyspnea, respiratory failure, or right heart failure. "Many studies have reported overexpression of all Class I and II HDACs, especially HDAC2 and HDAC4, in pulmonary fibrosis." (PMID 37893021, 2023). "Oxidative stress and epigenetic alterations, including the overexpression of all class I and II histone deacetylases (HDACs), particularly HDAC2 and HDAC4, have been identified as key molecular mechanisms driving pulmonary fibrosis." (PMID 37893021, 2023). "HDAC4 has been suggested as an important factor in pulmonary fibrosis being able to modulate extracellular matrix (ECM) production in pulmonary myofibroblasts." (PMID 37373058, 2023). "It was reported that HDAC2 was crucial for the chronic progression of lung fibrosis, while HDAC4 was crucial for the initial response to lung fibrosis." (PMID 37893021, 2023). "Aberrant HDAC enzyme activities are evident in fibrotic diseases, of which HDAC4 is important in lung fibrosis by modulating the production of ECM in lung myofibroblasts." (PMID 36203777, 2022). "Mechanistically, we also demonstrated that intraperitoneal TSA administration can suppress the activation of HDAC4 and downstream Akt, and attenuate the subsequent pulmonary fibrosis by inhibiting EMT." (PMID 28234968, 2017). "In the present study, we demonstrated that TSA prevented EMT and increases in MMP-9 and PAI-1, collagen 1a1, total collagen, and lung fibrosis parameters through the inhibition of HDAC4 activation in vivo." (PMID 28234968, 2017). "Furthermore, HDAC4 are important in pulmonary fibrosis, being able to modulate extracellular matrix (ECM) production in pulmonary myofibroblasts." (PMID 37373058, 2023). "In particular, the pulmonary expression of nuclear HDAC4 significantly increased following MV-augmented lung fibrosis compared with HDAC2; this indicates that class II HDAC4 intensely translocated from the cytoplasm into the nucleus in the injured lungs, whereas class I HDAC2 was not altered." (PMID 28234968, 2017). "In contrast to HDAC4 and HDAC7, much less is known about the role and functions of HDAC5 and HDAC9 in lung fibrosis." (PMID 35626663, 2022).
rheumatoid arthritis (6 papers, 2017 to 2023). A chronic, systemic autoimmune disorder characterized by inflammation in the synovial membranes and articular surfaces. "Meanwhile, HDAC4 modulates inflammation in diverse pathological conditions, such as rheumatoid arthritis, asthma, and atherosclerosis, while inflammation is one of the hallmarks of autoimmune diseases." (PMID 35602496, 2022). "And, HDAC4 is one of the most hyper-methylated genes outside the MHC region on CD4+ T cells from rheumatoid arthritis patients." (PMID 28177888, 2017). "Regarding the role of HDAC4 in autoimmune diseases, it was revealed that inhibition of HDAC4 promotes the proliferation and migration of fibroblast-like synoviocytes; it also exacerbates pathological damage in rheumatoid arthritis rats." (PMID 35602496, 2022). "Moreover, the HDAC4/PGRN and HDAC4/nuclear factor‐κB axes have been involved in the regulation of inflammatory cytokines in rheumatoid arthritis." (PMID 36039643, 2022). "Recent studies by Wang and Peng reported the role of GAS5 in hypoxic-ischemic brain damage and rheumatoid arthritis progression via the miR-128-3p/BAX axis and miR-128-3p/HDAC4 axis." (PMID 36672566, 2022).
urothelial carcinoma (6 papers, 2018 to 2024). A malignant neoplasm derived from the transitional epithelium of the urinary tract (urinary bladder, ureter, urethra, or renal pelvis). "Here, we aimed to address whether inhibiting HDAC4 might contribute to the therapeutic efficacy of HDACi in urothelial carcinoma." (PMID 30064501, 2018). "In conclusion, according to global gene expression analyses, the class IIA HDAC4 and HDAC5 are both lower expressed in urothelial carcinoma than in normal bladder tissue." (PMID 31052182, 2019). "Moreover, in a previous screen of HDAC4 expression, we observed strong expression of the protein in normal urothelial cells, but diminished expression in some, albeit not all urothelial carcinoma cell lines (UCCs)." (PMID 30064501, 2018). "Furthermore, evidence shows that overexpression of HDAC4 does not typically enhance urothelial carcinoma cell proliferation, suggesting that targeting HDAC4 with HDACis may not be effective in treating urothelial carcinoma." (PMID 38822399, 2024). "In conclusion, our data suggest that at least HDAC4, among the class IIA HDACs, does not significantly contribute to proliferation and survival of common urothelial carcinoma cell lines." (PMID 30064501, 2018).
acute myeloid leukemia (5 papers, 2021 to 2024). Acute myeloid leukemia (AML) is a group of neoplasms arising from precursor cells committed to the myeloid cell-line differentiation. "SIK2 has a role in tumorigenesis in prostate and ovarian cancers, and SIK2 and SIK3 promote the growth of acute myeloid leukemia (AML) by inhibiting HDAC4 function." (PMID 39139449, 2024). "This ambiguity is observed also for HDAC4 in hematological malignancies and particularly in the development of acute myeloid leukemia (AML)." (PMID 36762207, 2023). "In studies conducted in acute myeloid leukemia (AML) models, it was observed that treatment with quercetin for 48 h at a concentration of 50 μM, decreased the levels of histone deacetylase 4 (HDAC4), Nrf2 and phosphoro-Nrf-2 (p-Nrf2)." (PMID 36613834, 2022).
brachydactyly mental retardation syndrome (5 papers, 2012 to 2025). "In humans, single-nucleotide polymorphisms (SNPs) in HDAC4 are associated with non-syndromic oral clefts, and haploinsufficiency of HDAC4 causes brachydactyly mental retardation syndrome (BDMR) [OMIM: 600430] with associated craniofacial abnormalities." (PMID 22676467, 2012). "In humans, HDAC4 deficiency is associated with non-syndromic oral clefts and brachydactyly mental retardation syndrome (BDMR) with craniofacial abnormalities." (PMID 22676467, 2012). "The mechanistic connection between PTHrP and HDAC4 also help explain why HDAC4 haploinsufficiency causes Brachydactyly mental retardation syndrome, which is phenotypically similar to Brachydactyly type E caused by mutations in PTHLH, the gene that encodes PTHrP." (PMID 38370361, 2024). "These include Brachydactyly Mental Retardation Syndrome (BDMR, MIM: 600430), caused by the deletion of the 2q37 chromosomal region containing HDAC4, and 2q23.1 deletion syndrome (MIM: 156200)." (PMID 40724914, 2025). "In humans, HDAC4 haploinsufficiency leads to brachydactyly mental retardation syndrome (BDMR, OMIM: 600430), also known as 2q37 deletion syndrome, characterized by craniofacial abnormalities, including a prominent forehead, midface retrusion, microcephaly, and a depressed nasal bridge." (PMID 35242053, 2022).
Cognitive impairment (5 papers, 2020 to 2025). Abnormal cognition is characterized by deficits in thinking, reasoning, or remembering. "Aberrant expression of HDAC4, which represses genes essential for synaptic function, plays a pivotal role in cognitive impairment." (PMID 40673140, 2025). "Previous research indicates that the abnormal HDAC4 expression plays a key role in the cognitive impairment of several brain diseases, such as mental disorders and neurodegenerative diseases." (PMID 35783128, 2022). "Our results demonstrate a novel, unanticipated capacity for stress in adolescence to buffer effects of adult trauma-like stress on a cognitive deficit characteristic of PTSD as well as HDAC4/5 and NE levels." (PMID 33087769, 2020). "Moreover, it has been found that offspring cognitive impairment in mice and derangements of synaptic plasticity induced by maternal low-fiber diet can be reversed by butyrate intake via regulating the activity of histone deacetylase 4 (HDAC4)." (PMID 39770976, 2024).
emphysema (5 papers, 2016 to 2023). "An in vivo and in vitro study using HDAC4 inhibitors suggested an anti-inflammatory role for this enzyme in patients with the emphysema phenotype." (PMID 37373058, 2023). "A further study of HDAC4 inhibitors in vivo and in vitro suggested that HDACs have an anti-inflammatory role in emphysema." (PMID 31817742, 2019). "In a mouse model of emphysema, HDAC4 was targeted by miR-22 to promote a Th17 response in antigen presenting cells (APCs)." (PMID 28177888, 2017). "Similarly, miR-22-3p is reported to inhibit HDAC4 to promote Th17-mediated emphysema in cigarette-smoke (4 month)-exposed C57Bl/6 mice lungs." (PMID 34769265, 2021). "Furthermore, only emphysema patients showed a significant reduction in HDAC3 expression, and only COPD unclassified have a significantly increased expression in the HDAC4 gene." (PMID 37373058, 2023). "From this observation we can infer that high levels of HDAC4 mediated by miR-22 down-regulation could be involved in the reduced TH17 response found in patients with COPD-BS, leading to a lower inflammatory response and a decrease in emphysema, in comparison with patients with COPD-TS." (PMID 31817742, 2019).